HOTTIP (HOXA distal transcript antisense RNA)
Diseases named in the same sentence as HOTTIP in open-access papers (continued):
Sharing a sentence is not in itself a finding about the gene and the disease.
cancer (continued). "Subsequent studies have found that HOTTIP is highly expressed in almost all cancers and can recruit epigenetic factors such as EZH2 or directly insert DNA double strands to form R-loops to promote cancer development." (PMID 36750826, 2023). "Although M1 and M2 macrophages confer opposing effects on tumor progression, the findings of this study revealed that cancer cells expressing HOTTIP increased the amounts of both M1 and M2 macrophages in vitro and in the nude mice animal model." (PMID 35210436, 2022). "HOTTIP is related to the occurrence and development of various malignant tumors, such as liver cancer, pancreatic cancer, esophageal squamous cell carcinoma and lung small cell carcinoma and is considered an essential oncogene." (PMID 35210436, 2022). "IHC staining revealed that significantly more Ki67+ cells were detected in HOTTIP-knockdown xenografts than in the other three groups, which suggested that HOTTIP inhibited cancer cell proliferation in vivo." (PMID 35210436, 2022). "In many cancer types, HOTTIP is frequently upregulated and plays critical roles in promoting cancer progression." (PMID 34983537, 2022). "As a critical regulator of multiple cancers, silencing of HOTTIP leads to suppression of cell proliferation and NLRP1 inflammasome-mediated pyroptosis." (PMID 36506086, 2022). "The data suggested that cancer cells expressing HOTTIP and M1 exosomes reeducated circulating monocytes into the M1 phenotype." (PMID 35210436, 2022). "Further analysis of the role of HOTTIP lncRNA in tumor cells showed that overexpression of HOTTIP prevents proliferation, migration, and invasion but induces apoptosis of cancer cells in vitro." (PMID 35550636, 2022). "Here, the CCK-8 and EdU assays indicated that HOTTIP overexpression inhibited cancer cell proliferation, though HOTTIP knockdown induced proliferation." (PMID 35210436, 2022). "More importantly, both cancer cells expressing HOTTIP and M1 exosomes reeducated circulating monocytes to express the M1 phenotype." (PMID 35210436, 2022). "In colorectal cancer, HOTTIP is overexpressed in mitomycin-resistant cancer cells and their exosomes." (PMID 35055115, 2022). "The rationale was that there is evidence for stem cell inducing activity of HOTTIP in different other cancers." (PMID 34322490, 2021). "Since a role of NF-κB is important for cancer stem cells, we evaluated the effect of HOTTIP silencing on NF-κB activation and found that silencing of HOTTIP resulted in significantly reduced activation of NF-κB." (PMID 34322490, 2021). "To understand the mechanism of HOTTIP action, we turned to cancer stem cell characteristics because of the reports that HOTTIP affects cancer stem cells." (PMID 34322490, 2021). "The role of HOTTIP in tumor cells have been widely studied showing that HOTTIP acts mainly as an oncogene in the majority of cancers." (PMID 34111710, 2021). "Recent studies indicate that WDR5 also interacts with long, noncoding RNAs (lncRNAs), such as HOXD-AS1 and HOTTIP, to facilitate gene transcription in cancer via lncRNA-guided histone H3K4 trimethylation." (PMID 34154613, 2021). "Our study has shown that when the expression levels of EV HOTTIP increase during the postsurgical follow up, the patient is highly likely to have cancer recurrence or metastasis." (PMID 34111710, 2021). "This lncRNA undergoes abnormal expressions in different cancers and it has been shown that HOTTIP is related to the increased proliferation and progression of cancer cells." (PMID 32664703, 2020). "A systematic review of PubMed, Embase, Medline, and Web of Science databases was performed to select eligible literatures relevant to the correlation between HOTTIP expression and clinical outcome of different cancers." (PMID 32566641, 2020). "The HOTTIP suppression in cancer cell lines of liver decreased the rates of cell invasion and increased chemosensitivity." (PMID 33028884, 2020).
cancer (continued). "In the present study, we performed a meta-analysis to investigate the relationship between HOTTIP expression and the survival in patients of several different kinds of cancers." (PMID 32566641, 2020). "Recent studies have demonstrated that HOTTIP was overexpressed in many cancers and played oncogenic roles in cancer progression." (PMID 32566641, 2020). "In line with the prognostic impact of HOTTIP levels in other cancers, high levels of HOTTIP correlated with worse TTR and worse OS in our early-stage NSCLC patients." (PMID 30819158, 2019). "In the present study, we also analyzed HOTTIP expression pattern and its prognostic value in many other types of cancers." (PMID 31032351, 2019). "HOXA transcript at the distal tip (HOTTIP) has been shown to be up‐regulated in a variety of cancers and is identified as an oncogenic long noncoding RNA." (PMID 30548190, 2019). "The role of lncRNA HOTTIP as an oncogene in varieties of human cancer including CRC has been extensively investigated." (PMID 30940774, 2019). "Accordingly, flow cytometry analysis indicated that HOTTIP depletion in both cancer cell lines increased the proportion of cells that underwent proliferation arrest." (PMID 29884766, 2018). "Recently, HOTTIP has drawn increasing attention among cancer-related lncRNAs, which have been demonstrated to regulate genes by various mechanisms including epigenetic modifications, lncRNA-miRNA and lncRNA-protein interactions." (PMID 28036281, 2017). "In this study, we performed a meta-analysis to investigate the relationship between HOTTIP expression and the survival in patients with various cancers." (PMID 28036281, 2017). "Our results suggested that cancer patients with high HOTTIP expression in tumor tissues were more likely to exhibit poor tumor differentiation, a poor clinical stage, LNM and DM than patients with low HOTTIP expression." (PMID 28938659, 2017). "Some meta-analyses focused on the association of lncRNAs such as BANCR, HOTTIP, CCAT2, and metastasis as well as prognosis of cancers; all of them were based on the lncRNAs detected in tissues." (PMID 29088881, 2017). "These aggregated results suggested that cancer patients with high HOTTIP expression were more susceptible to LNM and DM than patients with low HOTTIP expression." (PMID 28938659, 2017). "We conducted this comprehensive meta-analysis to evaluate the relationship of lncRNA HOTTIP expression with prognostic results and clinicopathological parameters in cancer patients." (PMID 28938659, 2017). "After further evaluation of the full articles, a total of 7 publications addressing the relationship between lncRNA HOTTIP and cancer LNM or OS were found to meet all of the inclusion criteria and used for data extraction." (PMID 27806342, 2017). "In this two-phase study, we systematically investigate the relationship between HOTTIP expression and the survival in patients with various cancers by a meta-analysis." (PMID 28036281, 2017). "In order to combine the results of previous studies about HOTTIP and cancer to arrive at a summary conclusion, we elucidated the relationships between HOTTIP expression levels and LNM and OS in cancer in the present meta-analysis." (PMID 27806342, 2017). "While there are observed correlations between HOTTIP and vitamin D receptor signaling as well as p21 silencing, the main role of HOTTIP described in cancer progression is its ability to utilize three-dimensional chromatin looping structures." (PMID 29113413, 2017). "HOTTIP has recently been shown to be dysregulated and play an important role in the progression of several cancers." (PMID 27733185, 2016). "HOTTIP has recently been found to play important roles in cancer cell growth, survival and migration/invasion." (PMID 27733185, 2016). "In HCC, however, to date, only a few studies implicated lncRNAs, such as MALAT1, HOTAIR, HOTTIP/HOXA13, H19, HULC, MEG3, in the cancer pathogenesis." (PMID 25686840, 2015).
cancer (continued). "It is well-established that HOTTIP plays many roles in various types of cancers." (PMID 40616679, 2025). "On the contrary, HOTTIP has divergent roles in different cancers." (PMID 40616679, 2025). "The majority of research on HOTTIP has focused on its dysregulation and oncogenic roles in cancer." (PMID 40616679, 2025). "Furthermore, cancer cells expressing HOTTIP and M1 exosomes reinduced circulating monocytes to express the M1 phenotype, providing new insights into HNSCC." (PMID 40612677, 2025). "Moreover, HOTTIP-based cancer vaccine design would be a milestone via reversed vaccinology approach." (PMID 40616679, 2025). "Also, HOTTIP inhibits apoptosis by regulating Bcl-2 family proteins and suppressing pro-apoptotic miRNAs, ensuring cancer cell survival." (PMID 40616679, 2025). "HOTTIP knockdown improves the sensitivity of cancer cells toward gemcitabine." (PMID 40352931, 2025). "HOTTIP plays critical roles in cancer cell growth, survival, migration, and invasion." (PMID 40004468, 2025). "Interestingly, HOTTIP facilitates cancer cell metastasis via Twist family bHLH transcription factor 1 (TWIST1)-WDR5-HOTTIP axis that regulates HOXA9 chromatin." (PMID 40616679, 2025). "HOTTIP has been identified as an oncogene that promotes cancer proliferation and tumorigenesis." (PMID 40624028, 2025). "Unfortunately, HOTTIP’s exact significance in diseases other than cancer is, however, poorly described by the majority of studies that have been published to date as they have focused on its dysregulation and oncogenic roles in cancer." (PMID 40616679, 2025). "Furthermore, subsequent investigations are required to study HOTTIP SNPs across various cancer types which in turn will facilitate the early detection of diseases, particularly at initial stages or lower grades and thus improving patient outcomes." (PMID 40616679, 2025). "Additionally, the heterogeneity of HOTTIP expression and function in different cancers complicates the development of universal therapeutic approaches." (PMID 40616679, 2025). "Despite its established importance in cancer, HOTTIP’s role extends beyond malignant conditions." (PMID 40616679, 2025). "Targeting HOTTIP’s interaction with miRNAs (e.g., miR-196b, miR-615-3p) or chromatin-modifying complexes could offer cancer-specific therapeutic benefits as well." (PMID 40616679, 2025). "HOTTIP downregulation enhances apoptosis in cancer cells by pro-apoptotic proteins overexpression, caspases activation, and inhibition of the phosphatidylinositol 3-kinase (PI3K)/Ak strain transforming (AKT)/mechanistic target of rapamycin Kinase (mTOR) signaling pathway." (PMID 38559560, 2024). "In addition, HOTTIP alters immune cell’s anti-cancer effects, thereby enhancing their immune evasion." (PMID 39049088, 2024). "The comprehensive role of HOTTIP in cancer progression remains an area for future exploration." (PMID 38473915, 2024). "In the age of individualized cancer treatment, targeted medicines intended to alter HOTTIP expression or obstruct its downstream signaling pathways may be a fresh idea." (PMID 38186456, 2023). "The lncRNA HOTTIP is frequently upregulated in human cancers, where it promotes cancer progression." (PMID 37854681, 2023). "Although the exact mechanisms remain unclear, HOTTIP is involved in cancer stem cells modulation by sponging miR-148a-3p." (PMID 38186456, 2023). "Until recently, HOTTIP had only been measured in cancer tissues and specimens." (PMID 38186456, 2023). "Previous studies reported that HOTTIP was up-regulated in a variety of cancers." (PMID 37392284, 2023). "Both HOTTIP overexpression and M1 exosomes promoted cancer cell apoptosis significantly." (PMID 35210436, 2022). "Furthermore, cancer cells expressing HOTTIP were noted to induce the polarization of both local M1 and M2 macrophages; however, M1 exosomes were observed to reprogram local TAMs into M1 macrophages." (PMID 35210436, 2022).
cancer (continued). "After being released by macrophages, cancer cells could take up exosomes, with HOTTIP being the key molecule functioning in cancer cells." (PMID 35210436, 2022). "Therefore, the function of HOTTIP in cancer cells was explored, for which overexpression of HOTTIP was found to inhibit proliferation, migration and invasion but induced apoptosis of cancer cells in vitro." (PMID 35210436, 2022). "However, in the past few years HOTTIP was discovered to be have a pivotal role in human tumorigenesis, being expressed in nearly all kinds of human cancers." (PMID 33767982, 2021). "Additionally, HOTTIP plays an important role in the promotion of cell proliferation by regulating the expression of its neighboring HOXA genes in various types of human cancers." (PMID 34464437, 2021). "HOTTIP was identified as the target of miR-192 and miR-204, which would inhibit HOTTIP expression through the Argonaute2-mediated RNA interference pathway, thereby inhibiting the proliferation of the cancer cells." (PMID 33849550, 2021). "The result showed that high HOTTIP expression could predict worse outcome in cancer patients, with the pooled hazard ratio (HR) of 2.34 (95% confidence interval (CI) 1.96–2.79, p < 0.0001)." (PMID 32566641, 2020). "Recently, some studies have reported the relevance of HOTTIP in cancer prognosis." (PMID 32566641, 2020). "LncRNAs may be considered as therapeutic targets and promising biomarker for cancer prognosis, and one of well- known lncRNAs with oncogenic role in solid tumors is HOTTIP." (PMID 32587834, 2019). "Long noncoding RNA HOTTIP plays important roles in the generation and progression of human cancers." (PMID 29486794, 2018). "Increased HOTTIP expression has been reported in various types of human cancers." (PMID 29884766, 2018). "In addition, our study was the first meta-analysis to show the significant association between the lncRNA ANRIL, MALAT1, HOTTIP, and HULC polymorphisms and cancer risk." (PMID 29802154, 2018). "As emerging evidence suggests that certain members of the HOXA cluster are involved in cancer progression, we hypothesized that HOTTIP might regulate the biological behavior of SCLC via regulation of the HOXA cluster." (PMID 29367594, 2018). "Overexpression of HOTTIP was positive correlated with tumor stage, poor overall survival, distant metastasis and lymph node metastasis, indicating that HOTTIP expression may serve as a potentical biomarker for poor prognosis in cancers." (PMID 29992790, 2018). "HOTTIP has been suggested as a potential prognostic biomarker for diverse cancers." (PMID 29884766, 2018). "As cell invasiveness ability is one of the hallmarks of cancer metastasis, we asked whether the overexpression of HOTTIP would display a more invasive phenotype as assessed by a matrigel invasion assay." (PMID 29884766, 2018). "HOTTIP has been found dysregulated in several types of cancers." (PMID 29495592, 2018). "Together, lncRNA HOTTIP may not only act as a potential therapeutic target, but also as a novel prognostic biomarker in cancer." (PMID 27806342, 2017). "The further comprehensive mechanism between HOTTIP and cancer was reported in continuance." (PMID 27806342, 2017). "Furthermore, knockdown of HOTTIP also inhibited cancer cells migration and significantly abrogated lung metastasis in mouse xenograft mode." (PMID 28036281, 2017). "It has demonstrated that HOTTIP was involved in the cancer progression." (PMID 28036281, 2017). "Further exploration of correlation between HOTTIP and cancer is definitely required." (PMID 27806342, 2017). "Recently, the involvement of the lncRNA HOTTIP in various cancers has been elucidated." (PMID 27806342, 2017). "Among these cancers, HOTTIP might regarded as an oncogene, and HOTTIP overexpression was correlated to enhanced cell proliferation, migration but reduced apoptosis." (PMID 27806322, 2016).
cancer (continued). "HOTTIP has been recently revealed as oncogenic regulator in different cancers, however, whether HOTTIP is involved in ESCC remains poorly understood." (PMID 27806322, 2016). "Recent reports have shown that HOTTIP is associated with cancer metastasis and is a negative prognostic factor in patients with liver and tongue cancer." (PMID 27144338, 2016). "Because emerging evidence suggests that certain members of the HOXA cluster are involved in cancer progression, we hypothesized that HOTTIP might regulate the biological behavior of PDAC via regulation of the HOXA cluster." (PMID 25889214, 2015). "Consistent with this hypothesis, several lncRNAs, such asPTENP1, HULC, GAS5, loc285194,HOTAIR as well as HOTTIP, have been identified as miRNA targets in various cancers, which provide further layers of understanding lncRNA regulation during carcinogenesis." (PMID 26710269, 2015). "Considering the role HOTTIP plays in cancer development and the oncogenes that it controls, it is very interesting to see that it could be downregulated without a direct RNA silencing strategy, providing new possibilities in targeting selected oncogenic lncRNAs." (PMID 38389889, 2024). "Therefore, targeting HOTTIP may beneficially improve the effectiveness of various kinds of anti-cancer drugs." (PMID 35055115, 2022). "Therefore, the function of HOTTIP in cancer cells was further explored." (PMID 35210436, 2022). "In addition, this research found that HOTTIP was positively correlated with HOXA13, and it was speculated that HOTTIP could play a cancer-promoting role in PC through HOXA13." (PMID 35565245, 2022). "Exosomal HOTTIP might be a biomarker for cancer diagnosis and prognosis." (PMID 33585440, 2020). "As a biomarker combination could be more powerful than a single biomarker, we decided to evaluate, in the same EV samples, the expression of other lncRNAs whose expression in tissue impacted prognosis in other cancers studied by our group, including HOTTIP, HOTAIR, HOXA11, and HOTAIRM1." (PMID 32244977, 2020). "Considering all the identified lncRNAs, HOTTIP’s abnormal expression had the significant impact on the survival of patients (HR = 1.16; P = 0.00132), our data was in agreement with an recent meta-analysis that high HOTTIP expression was significantly correlated with poor OS in cancer patients." (PMID 30886579, 2019). "Although, a systematic review and meta-analysis has introduced HOTTIP as a lymph node metastasis indicator in human cancers including CRC, but the authors state that their results may be influenced by ethnic bias because the majority of studies have been conducted on population samples in China." (PMID 32587834, 2019). "In addition, functional prediction of SNP revealed that rs1859168 could alter HOTTIP expression by influencing the transcription factor binding sites, and HOTTIP takes part in regulating cancer cell proliferation and survival." (PMID 28818070, 2017). "The expression pattern of HOTTIP splice variants has never been detected in cancer tissue." (PMID 26447755, 2015). "Researchers have recently discovered a relationship between HOTTIP expression and the overall survival, distant metastasis, lymph node metastasis (LNM), and tumor stage of human cancers." (PMID 40616679, 2025). "A possible link between HOTTIP expression and tumor aggressiveness has been suggested by the higher median HOTTIP values seen in patients with multifocality and advanced stage III cancer." (PMID 38186456, 2023). "Then we detected the expression of HOTTIP and HOXA13 in clinical NPC patients and demonstrated the increased expression of HOTTIP and HOXA13 in cancer tissues, compared with those in paired normal tissues." (PMID 37392284, 2023). "DLEU2, HOTTIP, and SNHG1 have also been reported as onco-lncRNAs in HCC, while LINC00853 is currently poorly understood for the role in cancer and deserved for further study." (PMID 37006626, 2023).